MTFMT (mitochondrial methionyl-tRNA formyltransferase)
Description:
Methionyl-tRNA formyltransferase that formylates methionyl-tRNA in mitochondria and is crucial for translation initiation.
Synonyms: FMT1; COXPD15; MC1DN27
Tractability: PROTAC: its protein half-life has been measured.
Gene: Protein-coding gene on chromosome 15 (65,001,512 to 65,029,643, reverse strand). Ensembl gene ENSG00000103707.
Subcellular location: Mitochondrion
Subcellular location (Human Protein Atlas): Nucleoplasm; Cytosol
Pathways (Reactome):
Metabolism of proteins: Mitochondrial translation initiation
Gene Ontology:
Molecular function: methionyl-tRNA formyltransferase activity; catalytic activity
Biological process: conversion of methionyl-tRNA to N-formyl-methionyl-tRNA; translational initiation
Cellular component: mitochondrion
Genetic constraint (gnomAD): Loss-of-function variants: 34 observed, 34.71 expected, observed/expected ratio (o/e) 0.98, 90% interval 0.74 to 1.3. The upper end of that interval is the gene's LOEUF score, 1.3, which puts it in group 5 of 6, group 1 being the genes least tolerant of losing a copy. Missense variants: 428 observed, 372.03 expected, observed/expected ratio (o/e) 1.15, 90% interval 1.06 to 1.25. Synonymous variants: 168 observed, 138.72 expected, observed/expected ratio (o/e) 1.21, 90% interval 1.07 to 1.38.
Gene-disease validity (ClinGen):
ClinGen rates the evidence that MTFMT causes each of these diseases.
Leigh syndrome (autosomal recessive): Definitive. A progressive neurological disease defined by specific neuropathological features associating brainstem and basal ganglia lesions.
Homologues: Orthologues: chimpanzee MTFMT (99% identical), macaque MTFMT (91% identical), dog MTFMT (88% identical), pig MTFMT (84% identical), mouse Mtfmt (78% identical), rat Mtfmt (78% identical), guinea pig MTFMT (78% identical), rabbit MTFMT (72% identical), tropical clawed frog mtfmt (56% identical), zebrafish mtfmt (46% identical), Drosophila melanogaster CG1750 (30% identical).
Diseases named in the same sentence as MTFMT in open-access papers:
MTFMT is named in the same sentence as 12 diseases in open-access papers, as found by Europe PMC text mining. Sharing a sentence is not in itself a finding about the gene and the disease. The quoted sentences say what the papers report.
Leigh syndrome (6 papers, 2013 to 2021). "Pathogenic variants in MTFMT have been associated with Leigh syndrome (LS) and mitochondrial multiple respiratory chain deficiencies." (PMID 30911575, 2019). "Exome sequencing identified compound heterozygous mutations in the recently discovered mitochondrial methionyl-tRNA formyltransferase (MTFMT) gene in two sisters with mild Leigh syndrome and combined respiratory chain deficiency." (PMID 23499752, 2013). "Mutations in MTFMT should be screened in patients with Leigh syndrome and combined respiratory chain deficiency." (PMID 23499752, 2013). "Our WES analysis reveals three heterozygous nuclear variants, MTFMT, NARS2, and EARS2, mapping in genes known to cause COXPD associated with Leigh syndrome." (PMID 35004675, 2021). "Deficiencies in mt-tRNAMet-formylation due to mutations in mitochondrial methionyl-tRNA formyltransferase (MTFMT, MIM: 611766) have been identified in a number of patients with Leigh syndrome and combined OXPHOS deficiency." (PMID 26016801, 2015). "Our mitochondrial metabolic and morphometric analyses lend credence to the three heterozygous variants, MTFMT, NARS2, and EARS2, mapping in genes linked to COXPD associated with Leigh syndrome, as a probable cause of the proband’s neurological manifestations and mitochondrial etiology." (PMID 35004675, 2021).
demyelinating disease (1 paper, 2025). A broad group of disorders that affect the myelin sheaths that cover the neurons. "Mutations in the mitochondrial methionyl-tRNA formyltransferase (MTFMT) gene have been associated with neuroimaging features resembling acquired demyelinating diseases such as MS and NMOSD." (PMID 41357216, 2025).
developmental delay (1 paper, 2020). "Patients with variants in MTFMT and NSUN3 have been described with microcephaly, developmental delay muscular weakness, and CPEO." (PMID 33426505, 2020).
mitochondrial encephalomyopathy (1 paper, 2015). A heterogenous group of disorders characterized by alterations of mitochondrial metabolism that result in muscle and nervous system dysfunction. "Mutations in mitochondrial methionyl-tRNA formyltransferase (MTFMT) have been identified in a number of patients presenting with mitochondrial encephalomyopathy." (PMID 25806043, 2015).
viral infections (1 paper, 2020). "MTFMT-silenced cells exhibited a weakened cellular response against viral infections, as judged by lower RNA expression levels of type I IFN and decreased protein secretion compared to that observed in control cells." (PMID 32636430, 2020).
bacterial infection (1 paper, 2020). "Therefore, we also tested the effect of MTFMT deficiency during bacterial infection, using a Shigella flexneri infection system." (PMID 32636430, 2020).
infection (1 paper, 2020). The state of being infected such as from the introduction of a foreign agent such as serum, vaccine, antigenic substance or organism. "MTFMT-silenced cells were more susceptible to intracellular infection, as examined by infection with RNA viruses and the intracellular bacterium Shigella flexneri." (PMID 32636430, 2020). "In contrast, in MTFMT-deficient cells, the nuclear translocation of p65 was significantly inhibited until 90 min after infection." (PMID 32636430, 2020). "To gain insight into how MTFMT deficiency attenuates cellular immune responses during the early phase of infection, we performed a genome-wide transcriptome profiling assay." (PMID 32636430, 2020). "Using methionyl-tRNA formyl transferase (MTFMT)-deficient cells, which exhibit impaired mitochondrial activity, we examined the role of mitochondrial integrity in regulating innate defense against infection." (PMID 32636430, 2020). "In this study, using MTFMT-deficient cells with defective mitochondria under basal conditions, the significance of mitochondrial integrity in regulating the innate defense against infection was elucidated." (PMID 32636430, 2020). "Since we observed altered mitochondrial structure and function in MTFMT-deficient cells, we wondered whether the cellular response to intracellular infection was similarly altered." (PMID 32636430, 2020). "To determine whether MTFMT deficiency along with mitochondrial alterations leads to massive cell death at the later stage of infection, which may explain the peculiar kinetics of intracellular bacteria within, we next examined the occurrence of cell death." (PMID 32636430, 2020). "Since cellular toxicity was not significantly altered by MTFMT silencing during the first hour of infection (right), we concluded that MTFMT deficiency increases the susceptibility of cells to S. flexneri infection." (PMID 32636430, 2020).
MTFMT also shares sentences with these, for which no sentence is quoted: colorectal cancer (1 paper); microcephaly (1); mitochondrial disease (1); neurological diseases (1); tumor (1).